S100A8 (S100 calcium binding protein A8)
Diseases named in the same sentence as S100A8 in open-access papers (continued):
Sharing a sentence is not in itself a finding about the gene and the disease.
neurological disorders (7 papers, 2014 to 2025). "Our findings underscore S100A8/A9’s significance as a promising biomarker and potential therapeutic intervention in neurological disorders." (PMID 40688076, 2025). "In neurological disorders, S100A8/A9 induces reactive oxygen species (ROS) production and microglial activation." (PMID 38332909, 2023). "The associations between S100A8/A9 and SLE, and the fact that S100A8/A9 is expressed in the CNS and has been associated with neurological disorders, prompted us to investigate the possible association between NPSLE and S100A8/A9." (PMID 35804434, 2022). "Although the results shown here are promising for consideration of S100A8 as a serum biomarker, the limitation is a high abundance of this protein in other neurological disorders with similar symptoms as GBM." (PMID 30808902, 2019). "Notably, S100A8/A9 and MMP-9 have also been implicated in neuroinflammatory processes in other neurological disorders characterized by CI, such as AD and MS." (PMID 38332909, 2023). "S100A8/A9 has an immunopathogenic role in various neurological diseases." (PMID 35804434, 2022). "The study did not include disease controls with primary psychiatric or neurological disease, and therefore we were not able to draw conclusions on the discriminatory abilities of S100A8/A9 from other conditions." (PMID 35804434, 2022). "Among them, LCN2, TIMP1, S100A8/9, and PRDX2 related to host response and/or inflammation in neurological disorders, could be used as potential biomarkers of brain pathology." (PMID 24695528, 2014).
renal disease (7 papers, 2017 to 2025). "Furthermore, patients with SLE with active renal disease had significantly higher urine/serum ratios of S100A8/A9 (p<0.05) and S100A12 as compared with individuals with no or inactive renal disease (p<0.005)." (PMID 32723832, 2020). "Notably, among these abnormally expressed proteins, 19 proteins were reported as kidney disease markers (Ada, Ambp, Anxa1, B2m, Camp, Col1a1, Cp, Ggt1, Glb1, Lgfbp7, Lifr, Lpl, Plau, Ptgds, S100a8, Serpinc1, Serpina3k, Tff1, and Vtn) (highlight in green)." (PMID 31708494, 2019). "Conversely, S100 levels in the serum did not correlate with extrarenal or renal disease activity in cSLE, although serum S100A8/9 and S100A12 levels were higher in patients with active SLE than in healthy control subjects." (PMID 29065913, 2017). "Furthermore, patients with active kidney disease exhibit higher levels of S100A8/A9 in their urine when compared with patients without active kidney involvement." (PMID 32723832, 2020). "In this study, we determined serum and urine concentrations of S100 proteins S100A8/A9 and S100A12 in adult-onset SLE with or without active renal disease." (PMID 32723832, 2020). "Urine S100A8/A9 and S100A12 levels were significantly higher (p<0.005 and p<0.05) in patients with active renal disease as compared with individuals with no or inactive renal disease." (PMID 32723832, 2020). "While serum S100A8/A9 levels were not different between patients with active renal disease compared with patients with SLE without or inactive renal disease, serum S100A12 protein levels were lower (p<0.005) in individuals with active renal disease." (PMID 32723832, 2020).
metabolic disease (6 papers, 2018 to 2023). A congenital disorder (due to inherited enzyme abnormality) or acquired (due to failure of a metabolically important organ) disorder resulting from an abnormal metabolic process. "Taken together, this study reveals that the bone marrow-derived S100A8+ immune cells play a key role in driving BAT aging via inhibiting sympathetic innervation and that targeting S100A8+ immune cells offer a potential treatment strategy for age-related metabolic disorders." (PMID 37268694, 2023). "S100A8 and S100A9 were identified as the potentially perturbed proteins, which were related to immunological disease and metabolic disease." (PMID 35540476, 2018).
cardiac disease (3 papers, 2022 to 2024). "In recent years, studies have found changes in S100A8/A9 expression in various cardiac diseases, and the trend in these changes is closely related to disease progression." (PMID 39329929, 2024). "NLR family pyrin domain‐containing 3 (NLRP3)/IL‐1β signaling axis has been demonstrated to mediate S100a8/a9‐induced myelopoiesis in heart disease." (PMID 38023700, 2023). "In the present study, using a cardiac disease-specific qPCR array, we identified the most significant change in S100a8 expression in cardiomyocytes after miR-21 mimic/inhibitor treatment." (PMID 35907209, 2022). "S100A8/A9 may have dual roles in different cardiac diseases and disease stages." (PMID 39329929, 2024).
respiratory diseases (3 papers, 2021). "And compared with S100A8 and S100A9, SA100A12 is more considered as a marker for respiratory diseases with neutrophilic inflammation." (PMID 34457122, 2021). "The analysis yielded seven SARS-CoV-2 specific genes including CSF2 [GM-CSF] (colony-stimulating factor 2) and calcium-binding proteins (such as S100A8 and S100A9), which are known to be involved in respiratory diseases." (PMID 34376762, 2021).
diseases of the urinary tract (2 papers, 2017 to 2022). "Numbers of S100A8/A9+ cells per mm2 were numerically smaller in dogs with UC (median: 22) compared to non-neoplastic urinary tract diseases (median: 312) but similar to the control group (median: 21)." (PMID 36411489, 2022).
hematological cancers (2 papers, 2017 to 2024). "In hematological cancers, S100A8 has been reported to be overexpressed in childhood AML and associated with a worse prognosis." (PMID 28183295, 2017).
neoplastic disorders (2 papers, 2017 to 2019). "Recent studies have shown that S100A8/S100A9 is associated with various neoplastic disorders." (PMID 31208368, 2019).
S100A8 also shares sentences with these, for which no sentence is quoted: Peptic ulcer (124 papers); atrophic gastritis (74); gastric diseases (61); gastric adenocarcinoma (59); gastric ulcer (36); adenocarcinoma (26); MALT lymphoma (26); Atrophy (24); gastrointestinal disease (19); H. pylori (17); dyspepsia (15); Barrett esophagus (12); gastrointestinal disorders (12); gastric MALT lymphoma (10); acute myocardial infarction (9); reflux esophagitis (9); gingivitis (7); migraine (6); diffuse large B-cell lymphoma (5); idiopathic thrombocytopenic purpura (5); iron deficiency (5); osteoporosis (5); autoimmune thyroid disease (4); IgA nephropathy (4); Parkinson disease (4); vitamin B12 deficiency (4); acne (3); acute promyelocytic leukemia (3); ankylosing spondylitis (3); childhood asthma (3).
A further 193 diseases each share a sentence with S100A8 in 3 papers or fewer.